CD4 (CD4 molecule)
Diseases named in the same sentence as CD4 in open-access papers (continued):
Sharing a sentence is not in itself a finding about the gene and the disease.
AIDS (continued). "A 44-year-old man with acquired immune deficiency syndrome (AIDS) and CD4+ cell count of 8 cells/mm3 presented with painful and erythematous swollen hands 1 month after starting antiretroviral therapy (ART) after a 4-year hiatus from care." (PMID 28959701, 2017). "Due to rapid loss of CD4+T cells leading to fast progression to AIDS, concerns on better linkage to care should be underlined." (PMID 28107523, 2017). "The most likely explanation of our finding is the presence of confounding by indication as, for a given high viral load, ART is typically initiated in people with lower CD4 count and with a higher risk of AIDS and death." (PMID 28129343, 2017). "CD4 count has been reported to be one of the best surrogate markers for monitoring the progression of HIV infection and low CD4 counts are associated with increased risk of developing AIDS or death." (PMID 28450993, 2017). "The authors found that deferring therapy to a CD4 count of 250–350 cells/μL was associated with higher rates of a composite endpoint of AIDS or death than deferring to 351–450." (PMID 39450053, 2017). "HIV-1 infects CD4+ cells such as macrophages and helper T cells and causes acquired immunodeficiency syndrome (AIDS)." (PMID 28761140, 2017). "Comprehensive natural history studies in Gombe National Park, Tanzania, revealed that SIVcpz-infected chimpanzees have a 10–16 fold increased risk of death and can develop CD4+ T cell depletion and AIDS-like immunopathology." (PMID 28576126, 2017). "In this study we have compared the difference in risk of short-term (3–12 months) progression to AIDS/death between people carrying predominantly R5 or X4 viruses, taking into account CD4+T-cell count and use of ART." (PMID 28129343, 2017). "One such chimpanzee (Goran), who was rescued in Cameroon and studied in captivity for several years, developed CD4 T+ cell decline, severe thrombocytopenia, weight loss, and recurrent infections, and ultimately died of an AIDS-like illness." (PMID 28576126, 2017). "In our study, we found that a lower CD4 count (350–499 cells/μL) at baseline was a risk factor for fast HIV/AIDS progression, in concordance with previous studies." (PMID 28484257, 2017). "It has been observed that the greater the severity of infection (AIDS, CD4+ T-cell count <200/μl), the greater the risk of thromboembolic complications." (PMID 28749986, 2017). "CD4+ T cells are key to anti-mycobacterial immune protection and CD4+ T-cell deficiency, e.g. of AIDS patients, results in increased susceptibility against tuberculosis." (PMID 28582466, 2017). "During late stages of infection mostly patients have AIDS-associated symptoms or immunodeficient with CD4 T cell count less than 200/μl." (PMID 28326304, 2017). "As expected, IDU and older age and lower CD4+ cell count were all significantly associated with increased all-cause, liver-related, and AIDS-related mortality." (PMID 28926400, 2017). "Gender, residence area, employment status, baseline WHO stage of the disease (AIDS) and level of CD4 counts were identified as risk factors for TB incidence." (PMID 28049455, 2017). "Research in recent years has indicated that early initiation of ART can delay time to AIDS-related events and decrease incidences of morbidity and mortality, and high current CD4+ T cell count can be associated with suboptimal adherence to ART11–17." (PMID 28600549, 2017). "While the survival rates among those on treatment have improved, a subset of patients (ranging from 15% to 40%) continue to experience sub-optimal CD4 T-cell recovery, which in turn has been associated with an increased risk of serious non-AIDS events (SNAEs)." (PMID 29016635, 2017). "The association with delayed ART for both baseline CD4 count and a prevalent AIDS diagnosis dissipated in the latter time period." (PMID 28700693, 2017).
AIDS (continued). "We wish to report unusual presentation of AIDS-associated BL in a 42-year-old female patient with severe CD4 cell count depletion and dramatic fast growing (within days) orbital, eyelid, and frontal masses." (PMID 27818811, 2016). "Although an improvement, other studies have demonstrated that PHA who initiate cART with CD4 cell measures below 350 cells/mm3 are at higher risk of AIDS and death than individuals who begin treatment at higher CD4 thresholds." (PMID 27769246, 2016). "5-year percentage risk of death (95% CI) from 10 years after start of ART, according to age, IDU risk group, AIDS status, CD4 count and viral suppression (HIV RNA <50 copies/mL)*." (PMID 27525413, 2016). "The hallmark of HIV infection is progressive depletion of CD4 T-cells leading to development of opportunistic infections (OIs), AIDS, and death." (PMID 26843068, 2016). "Investigation of HIV-1 associated TB has focussed on deficient CD4 T cell responses which are evident before severe depletion of circulating CD4 T cells in AIDS." (PMID 26986567, 2016). "In a study conducted in AIDS patients with TE at admission in intensive care units, the factors independently associated with a poor outcome were a Glasgow coma scale ≤8 and a CD4 cell count <25/μL." (PMID 27355620, 2016). "They showed that migration status constitutes a risk factor for late clinical presentation (AIDS prior to the first visit in a ClinSurv centre or CD4-count lower than 350 cells/ul) to HIV care centres." (PMID 27927190, 2016). "CD4+T cell deficiency and function disruption are hallmarks of acquired immunodeficiency syndrome (AIDS), caused by the human immunodeficiency virus (HIV)." (PMID 27528225, 2016). "The vast majority of cryptococcal infections occur among individuals with impaired cell-mediated immunity, and the marked susceptibility of persons with AIDS demonstrates the importance of CD4+ T lymphocytes in protection." (PMID 26768248, 2016). "The CD4 count is the main risk predictor for progression to AIDS and death among HIV-positive patients." (PMID 27191248, 2016). "It was recently proposed that, during pathogenic HIV/SIV infections, high levels of direct virus infection of TCM contribute to the progressive depletion of total CD4+ T-cells which is typically associated with progression to AIDS." (PMID 27227993, 2016). "We report unusual presentation of a fatal case of AIDS-associated BL in a 42-year-old female patient with severe CD4 cell depletion who presented with dramatic fast growing (within days) bilateral orbital masses leading to striking facial deformities." (PMID 27818811, 2016). "Advanced HIV disease, as evidenced by low CD4 cell count and AIDS events, is associated with lower rates of VL suppression on HAART." (PMID 27449671, 2016). "We previously found that high cumulative VL on HAART was associated with a greater than 2-fold increase in AIDS events and impacted overall CD4 gains." (PMID 27449671, 2016). "HIV-1 is well known as the causative agent of acquired immune deficiency syndrome (AIDS) which develops via the progressive depletion of CD4+ T cells." (PMID 26751489, 2016). "HIV-1 infection causes acquired immune deficiency syndrome (AIDS), which is characterized by a significant reduction in CD4+ T cells and damage to the immune system." (PMID 27869733, 2016). "Noteworthy, HIV-infected individuals that maintain a CD4+ T cell count above 500 cells/μL have been shown to have lower risk of both AIDS and all cause mortality." (PMID 27769179, 2016). "HIV/AIDS patients having lower CD4 count (<200 cells/cumm) are at higher risk of cryptosporidiosis, with severe infections below 50 cells/cumm CD4 count." (PMID 26981284, 2016). "The number of OI cases and associated costs averted if ART was initiated at a CD4 count ≥200 cells/μL were estimated using Joint United Nations Programme on HIV/AIDS (UNAIDS) country estimates and global average OI treatment cost per case." (PMID 26951573, 2016).
AIDS (continued). "A previous study demonstrated that patients with a CD4 count<200 cells/μL at baseline are at a higher risk for AIDS in particular, but also for non-AIDS-related mortality." (PMID 27025828, 2016). "Multivariate Cox proportional-hazard models on the risk of any type of malignancy, the risk of AIDS-defining malignancies, and the risk of non-AIDS-defining malignancies (including CD4/CD8 ratio)." (PMID 27603338, 2016). "Generally, risk factors for developing cancer among PLWHA include low CD4 cell count or late stage of AIDS, co-infection with other viruses, cigarette smoking, alcohol consumption, and advanced age." (PMID 26883427, 2016). "Persistent human immunodeficiency virus type 1 (HIV-1) infection causes a progressive loss of CD4+ T cells, followed by acquired immunodeficiency syndrome (AIDS)." (PMID 27527606, 2016). "In several studies, a cutoff of CD4+ T-cell count 200 cells/μl has been defined as a critical threshold for the risk of AIDS events or death." (PMID 27427875, 2016). "This suggests “direct” death of productively infected cells contributes minimally towards AIDS progression, and bystander cell killing appears to be the leading cause for CD4 T cell loss and AIDS progression." (PMID 27026376, 2016). "It is important to note that the current studies were not extended to include late stages of disease characterized by CD4 + T cell loss and AIDS." (PMID 26908312, 2016). "Even in this cohort of patients who have survived at least ten years on ART, traditional markers of HIV progression such as CD4 count, viral load, and AIDS events remain important risk factors warranting clinical attention." (PMID 27525413, 2016). "HIV/AIDS causes severe dysfunction of the immune system through CD4+ T cell depletion, leading to dysregulation of both the adaptive and innate immune arms." (PMID 27256449, 2016). "Elevated IP-10 levels at M3 post-SC were also associated with rapid CD4+ T-cell decline to below 350/mm3 and with an increased risk of rapid progression toward AIDS (OR = 2.54 p = 0.02) before any treatment." (PMID 27509048, 2016). "CD4 T cell depletion during HIV-1 infection is associated with AIDS disease progression, and the HIV-1 Env protein plays an important role in the process." (PMID 27026376, 2016). "On univariate analysis of dichotomous variables, variables with the strongest association with biomarker levels were: AIDS, current CD4 <200 cells/m3, smoking (past or present), and co-infection with HCV." (PMID 26641655, 2015). "CD4 cell count has been reported to have a strong association with progression to AIDS-related illness or death." (PMID 26370702, 2015). "Like HIV, it enters host cells through CD4+ surface proteins and causes CD4+ T cell depletion, resulting in immunodeficiency that progresses to an AIDS-like state with opportunistic infections, muscle wasting, and neurological problems." (PMID 26695751, 2015). "In our cohort, failure to increase CD4+ T-cell count from below to more than 200 cells/μl after 1 year of effective HAART increased the subsequent risk of severe non AIDS-related event by 65%." (PMID 26020949, 2015). "Depletion of CD4 cells, such as occurs during advanced AIDS, is known to be a critical risk factor for developing cryptococcosis." (PMID 26252005, 2015). "One of the major hallmarks of HIV infection is the immune activation that prompt viral replication and CD4+ T cells loss with disease progression, also leading to an impaired immune competence and consequently to AIDS development." (PMID 26568963, 2015). "The depletion of CD4+ T cells is a hallmark of HIV disease progression, which makes CD4+ T-cell counts a powerful predictor of the short-term risk of progression to AIDS." (PMID 26436092, 2015). "The secondary endpoints were hepatotoxicity-requiring interruption of TB therapy, TB-associated immune reconstitution inflammatory syndrome, new AIDS defining illnesses, CD4 counts, HIV RNA levels, and AFB smear conversion rates." (PMID 25966339, 2015).
AIDS (continued). "Advanced immunosuppression as reflected by a lower baseline CD4 lymphocyte count or AIDS at diagnosis was a risk factor in HIV co-infected patients." (PMID 26406228, 2015). "A low CD4 lymphocyte count at diagnosis in 5/8 studies (63%) and an AIDS diagnosis in 2/2 studies were significant risk factors for ADR amongst HIV-infected patients." (PMID 26406228, 2015). "Previously published data from the D.A.D and CASCADE studies showed a clear increase in the rate of death from non-AIDS causes in patients with CD4 counts of 200–349 mm3 compared with those with CD4 counts of >500 mm." (PMID 26641655, 2015). "Typically, progression to a CD4 count of <200 cell/mm3 or AIDS appears to require the mutation at Arg-264 which abrogates binding of KK10 to HLA-B*27, and therefore would abolish the CD8+ T-cell response altogether, whereas L268X merely reduces recognition." (PMID 26834742, 2015). "AIDS and other immune compromising disorders are associated with increased rates of opportunistic fungal infections due to CD4+ T cell lymphopenia." (PMID 26367276, 2015). "This has been previously illustrated for HIV infection, where CD4 counts and mRNA viral load are correlated with clinical status, antiviral treatment effect, and risk of AIDS." (PMID 25994981, 2015). "Two large cohort studies have assessed the risk of death and AIDS at latest CD4+ cell counts above 350 cells." (PMID 25856495, 2015). "As CD4/CD8 ratio inversion has been associated with non-AIDS morbidity and mortality, predictors of ratio normalization after cART need to be studied." (PMID 26485149, 2015). "On the other hand, X4 HIV-1 is strongly associated with T CD4 positive T lymphocyte count decay, which is a hallmark towards AIDS development and a parameter for clinical evolution." (PMID 26413773, 2015). "Our results also indicate that a higher CD4+ T-cell count was associated with a lower rate of AIDS progression (HR = 0.380, 0.187, P < 0.001)." (PMID 26413133, 2015). "Patients failing to restore CD4+ to >200 cells/μl run a greater risk of serious nADE, which is intertwined or predicted by AIDS progression." (PMID 26020949, 2015). "The x4, dual tropic and dm viruses have been associated with rapid CD4 declines and progression to AIDS and death but the prevalence/appearance of x4, dm and dual tropic HIV-1 was originally described for subtype B infections." (PMID 26435727, 2015). "Conversely, an inverse association emerged between early mortality risk and CD4 cell count, particularly for PWA with a CD4 cell count lower than 50 CD4 cells/mm3 at AIDS diagnosis (OR = 1.87; 95 % CI: 1.55-2.27 vs. ≥350 CD4 cells/mm3)." (PMID 26067992, 2015). "A reduction in CD4 T cells below 200 cells/uL makes the host highly susceptible to opportunistic infections and increases overall AIDS related morbidity and mortality." (PMID 26448332, 2015). "Male gender, clinical AIDS (stage of disease) and low CD4 count were all significantly associated with anaemia at enrolment." (PMID 26474481, 2015). "Patients on suppressive ART who present with lower CD4:CD8 ratios have a higher risk for non-AIDS morbidity and mortality even with optimal CD4 T cell recovery." (PMID 26130226, 2015). "A previous study indicated that a down-regulated CD39 expression in CD4 T cells was associated with a slower progression to AIDS." (PMID 26367535, 2015). "Apoptosis is a hallmark of HIV infection and increased AICD is thought to contribute to the gradual loss of CD4+ helper cells during progression toward AIDS." (PMID 26441939, 2015). "Failure to reach a normal CD4/8 ratio is associated with an increased frequency of non-AIDS events and death." (PMID 26355305, 2015). "The clinical evidence in AIDS associated cryptococcosis unequivocally demonstrates that CD4 T cell mediated immunity is paramount to the host resistance to cryptococcosis." (PMID 26252005, 2015).
AIDS (continued). "In a big cohort of collaborative study from Europe and North America show that baseline CD4 cell count was strongly associated with the probability of progression to AIDS or death." (PMID 26090021, 2015). "Among people diagnosed with HIV from 1996 to 2010, age and baseline CD4 counts were significantly associated with the development of AIDS." (PMID 25095830, 2014). "The majority of HIV-infected individuals experience progressive infection, characterized by ongoing virus replication, CD4(+) cell depletion, and eventually acquired immune deficiency syndrome (AIDS)." (PMID 25418588, 2014). "As expected, the association with low CD4 cell count was strong for AIDS events with a dose–response pattern." (PMID 24885790, 2014). "Sensing of reverse transcripts by IFI16 in quiescent CD4+ T cells induces cell death, which is thought to contribute to CD4+ T cell loss and progression to AIDS 73,74." (PMID 24782340, 2014). "Smaller CD4 gains by six months were associated with higher hazards of progression to AIDS (CD4<50 vs. ≥200 cells/ml; adjusted hazard ratio (aHR): 2.6; 95% CI: 1.2–2.1) and death (aHR: 2.8; 95% CI: 1.4–5.7)." (PMID 24594114, 2014). "Previous analyses of EuroSIDA data demonstrated that current CD4 count is a significant predictor of the risk of non-AIDS events although the association was less strong than that found for AIDS events." (PMID 24498036, 2014). "Among treated adults with spectrum of CD4+ T cell counts, the ratio appears to correlate with markers of T cell activation and senescence and with the risk of non-AIDS morbidity and mortality." (PMID 24831517, 2014). "After adjusting for current CD4, only a tendency for an association between ID and the risk of non-AIDS remained (aRR 1.43, 95% CI 0.94–2.17,p = 0.095)." (PMID 24498036, 2014). "The virus replicates within and destroys CD4+ T cells in patients, ultimately leading to acquired immune deficiency syndrome (AIDS)." (PMID 25487036, 2014). "In this study in ART-treated HIV-infected patients, a low CD4/CD8 ratio was strongly associated with the risk of non-AIDS morbidity and mortality." (PMID 24497929, 2014). "We found that female sex, younger age, prior AIDS, and a lower CD4 count at baseline were associated with a higher hazard of experiencing the composite endpoint." (PMID 25221931, 2014). "For individuals living with HIV, late diagnosis (lower CD4 count, higher viral load, or an AIDS-defining illness) has been associated with a greater probability of progression to AIDS and death." (PMID 25372464, 2014). "Continuous CD4+ T cell loss eventually leads to AIDS as the regenerative capacity of the immune system gradually decreases despite the excess of homeostatic cytokines." (PMID 25228901, 2014). "Outcomes documented included time to development of AIDS and/or death, resistance mutations, opportunistic infections, and changes in CD4 cell counts and viral load." (PMID 24998532, 2014). "We previously showed that a severe depletion of CD4+ T-cells is associated with increased viremia, emergence of CD4-independent viruses and rapid progression to AIDS in SIV-infected RMs." (PMID 25356757, 2014). "In the majority of cases, HIV infection is characterized by high levels of viral replication, progressive loss of CD4+ T cells, and if left untreated, eventual progression to AIDS." (PMID 25167059, 2014). "PCNSL is also an AIDS-defining condition associated with a very low CD4 T-cell count (<50 cells/mL)." (PMID 25254131, 2014). "In SIV-infected Asian monkeys (Rhesus macaques and pigtail macaques, e.g.)AIDS develops, associated with persistent immune activation and rapid CD4+ T-cell loss." (PMID 25077616, 2014). "In adjusted analyses, ART-naïve (n = 1937) and ZDVm-experienced (n = 91) women had similar increases in CD4 count and a similar proportion achieving virological suppression; both groups had a low risk of AIDS." (PMID 24593018, 2014).